ITGAV (integrin subunit alpha V)
Diseases named in the same sentence as ITGAV in open-access papers (continued):
Sharing a sentence is not in itself a finding about the gene and the disease.
tumor (continued). "ITGAV is a transmembrane glycoprotein responsible for cell-to-matrix binding, which is physiologically almost undetectable and has been found be a marker for tumor progression in multiple tumor entities." (PMID 35246597, 2022). "ITGAV activation, which has been shown to act either as tumour suppressor or oncogéne." (PMID 34490102, 2021). "ITGAV is also involved in angiogenesis, which may facilitate tumor growth independently to the direct effects of the integrin signaling pathway on cancer cell proliferation." (PMID 33718208, 2021). "We could demonstrate that the knockdown of ITGAV led to a massive reduction in intraperitoneal carcinomatosis, primary tumor growth and pulmonary metastasis." (PMID 34174926, 2021). "The proportion of migrating tumor cells was reduced for both cell lines upon ITGAV KD (P < 0.001)." (PMID 34174926, 2021). "Therefore, to investigate the potential function of ITGAV in ESCC patient‐derived tumours, a lentivirus‐transduced PDX mouse model was generated." (PMID 34709754, 2021). "In particular, Wnt5A-induced ITGAV may be important in increasing tumor cell adhesion, proliferation, and migration contributing to OVC progression." (PMID 33723319, 2021). "Protein levels of ITGAV were determined in human ESCC tumour tissues using immunohistochemistry." (PMID 34709754, 2021). "Specific inhibition of ITGAV may have the potential to impede intraperitoneal carcinomatosis, tumor growth and distant metastasis." (PMID 34174926, 2021). "Additionally, inhibition of ITGAV has been shown to reduce tumour growth and metastasis in a variety of cancers." (PMID 34709754, 2021). "High risk of tumor recurrence, according to the 2015 American Thyroid Association guidelines, was associated with higher ITGA3 expression, whereas higher expression of ITGA2 and ITGAV correlated with intermediate-risk." (PMID 34208249, 2021). "In cross table analysis a correlation between ITGAV expression, older patients (> 65 years) and advanced tumor staged could be revealed (p = 0.05 and p = 0.005, respectively)." (PMID 33110104, 2020). "This clearly identifies ITGAV as a promoter of tumor progression for EAC." (PMID 33110104, 2020). "Genes encoding for integrins (such as ITGAV, ITGBL1, and ITGB1) that can promote tumor cell proliferation and migration and genes related to the Hippo signaling pathway, one of the signaling pathways which has been implicated in cancer by promoting cell proliferation, were also downregulated." (PMID 32616706, 2020). "Among the proteins from tumor stroma, the protein ITGAV is a receptor of ECM and serves as a subunit for receptors of integrins, RGD-motif bound containing substrates, such as vitronectin, fibronectin and fibrinogen, which are components of the stroma involved in the EMT transition." (PMID 30185791, 2018). "The majority of proteins (ACTR2, CSTB, LTA4H, PGK1, NDRG1, FSCN1, ITGAV, THBS2) significantly associated with clinical parameters showed lower expression in the ITF of the tumor stroma or neoplastic islands, with the exception of COL6A1, COL1A2, S100A8, S110A9, and MB." (PMID 30185791, 2018). "In addition to blocking VEGFR2, YLL545 altered the expression of other molecules involved in tumor angiogenesis, including ITGAV, ENG, THBS1, FN1, and TEK." (PMID 27203384, 2016). "Moreover, the CM-FLF-induced apoptosis resistance or chemotaxis of tumor cells was attenuated when ITGAV, the common receptor of FN1 and SPP1, was silenced by RNA interference or blocked by GRGDS treatment in tumor cells." (PMID 27329720, 2016). "ITGAV is the vitronectin receptor integrin (integrins mediate attachment between a cell and its surroundings); vitronectin is found in serum and the extracellular matrix (ECM) and has been implicated in tumour malignancy." (PMID 24400102, 2014). "The 38 tumor cell lines expressed the genes encoding αv (ITGAV, expression signal above 10 in most cases, data not shown), and β5 integrin chains (ITGB5)." (PMID 23977342, 2013).
tumor (continued). "In addition, correlation analysis also indicates that ITGAV may be involved in tumor immunity by regulating macrophage and Th17 cell function." (PMID 40018050, 2025). "Previous studies indicated that ITGAV may play a promotional role in the malignant progression of digestive system cancers by engaging in signaling pathways that enhance the migration and movement of tumor cells." (PMID 40018050, 2025). "Similarly, analysis of CCLE data indicated that tumor cell lines derived from tissues such as ovaries, livers, kidneys, and fibroblasts expressed relatively high levels of ITGAV, whereas those derived from the small intestine and prostate expressed relatively low levels." (PMID 40775249, 2025). "Therefore, we sought to determine whether ITGAV could participate in tumor immunity by modulating the function of CAFs." (PMID 40018050, 2025). "It suggested that ITGAV may contribute to creating a conducive environment for tumor growth, dissemination, and metastasis by regulating the infiltration of CAFs, thereby informing the development of clinically effective new treatments for digestive system cancers." (PMID 40018050, 2025). "Consistent with the results observed in tumor relapses, Met-M samples slightly reduced the percentage of Ecad+ cancer cells and were enriched in Vim+ and ITGAV+ cancer cells compared with Met-PT samples, with both conditions showing a similar percentage of ITGAV+Vim+ cancer cells." (PMID 39075581, 2024). "Both KEGG and GSEA revealed that ITGAV may be involved in tumor immune response." (PMID 36388191, 2022). "The expression levels of integrin subunit alpha V (ITGAV) and integrin subunit beta 5 (ITGB5) were significantly increased in tumor tissues and correlated with poor prognosis of HCC patients." (PMID 41018265, 2025). "In SMAD4‐null BxPC‐3 cells, ITGAV KO reduced ERK phosphorylation, indicating an alternate signaling pathway and potential compensatory role for MAPK/ERK signaling in supporting tumor cell motility when TGF‐β/SMAD signaling is impaired." (PMID 40739706, 2025). "Integrin αv (ITGAV, CD51) is one of the crucial members of the integrin family and is regarded as a key component in multiple stages of tumor progression." (PMID 40018050, 2025). "The levels of ITGAV, ITGB3 and ITGB5 were significantly higher in GBM samples than in non-tumor specimens." (PMID 40281508, 2025). "The majority of DEGs related to this pathway (ITGAV, KDR, VEGFB, AKT1, VEGFA) were downregulated in tumor cells except for HSBP1 and SHC2." (PMID 39245631, 2025). "Accordingly, CRISPR‐mediated KO of ITGAV led to decreased proliferation and migration across all PDAC cell lines tested, underscoring the broad functional importance of this integrin in tumor cell growth and motility." (PMID 40739706, 2025). "As a result, we identified a requirement for integrin αV (ITGAV) and integrin β5 (ITGB5) in tumor cell maintenance." (PMID 38316881, 2024). "The results from the present study, in particular, show that CD44 expression was increased in the st-FL tumor along with several members of the CD11a/b family (ITGA1, ITGA5, ITGB1, ITGAV), and all integrins were involved in cellular adhesion and migration." (PMID 39456647, 2024). "Specifically, SPP1 released from tumor cells interacted with CD44, ITGAV, ITGA5, ITGB1, and ITGB5 on immune clusters." (PMID 39505867, 2024). "We demonstrated that stromal colocalization of ITGAV and COL4A1 in the IO-exposed TIME is increased among fibroblasts, tumor cells, and endothelial cells." (PMID 39639369, 2024). "Among stromal fibroblast cells, ITGAV, ITGA1, ITGB1, and ITGB5 were significantly upregulated following IO and, notably, isolated tumor cells found in the stroma showed upregulation of B2M, VIM, ITGA5, ITGB2, and ITGA3." (PMID 39639369, 2024).
tumor (continued). "We further demonstrate that the activation of insulin-like growth factor-1 receptor (IGF1R) signaling pathway in epithelial cancer cells promotes ITGAV expression and induces EMP in response to tumor microenvironment (TME)-derived factors." (PMID 39075581, 2024). "Reduced expression of eight immune‐related genes (IRGs) (NT5E, THRA, RBP1, TLR4, ITGA6, BMPR1B, ITGAV, SSTR1) in tumor strongly predicted better quality of prognosis, both in our patient cohort and in TCGA‐HNSC cohort." (PMID 37392167, 2023). "Our findings indicate that ANGPTL3 and ANGPTL8 play a pivotal role in cancer progression by interacting with tumor-suppressor proteins such as ITGB3, ITGAV, RASSF5, and FNDC5." (PMID 37375208, 2023). "Tumor samples with more than 4 mm thickness exhibited significantly lower relative expression levels of ITGA3, ITGA6, ITGA9, ITGAV, and ITGB1 than samples belonging to the 2–4 mm Breslow thickness category (Mann–Whitney test, p < 0.05)." (PMID 36091936, 2022). "These cells highly expressed the integrin family genes associated with the cell adhesion molecule pathway in contrast to epithelial tumor cells, such as ITGA2, ITGA3, ITGA5, ITGA6, and ITGAV, which were among the top-ranking DEGs." (PMID 36553542, 2022). "Additionally, ITGAV/B1 is important to the fibronectin binding and retention of metastatic EVs, which we previously demonstrated to be taken up by a variety of stromal cells in the tumour microenvironment, including fibroblasts, endothelial cells, and immune cells." (PMID 35923105, 2022). "To confirm this result, we co‐stained the tumour sections with fluorescent anti‐human CD63 and anti‐human ITGAV antibodies and examined them using confocal microscopy." (PMID 35923105, 2022). "We then analyzed the expression profiles of COL1A1, COL4A1, and COL6A2 in TAF and ITGA2, ITGAV, and ITGA1 in tumor cells." (PMID 35322024, 2022). "We observed that CA1a tumours had more localisation of CD63 and ITGAV than MB‐231 tumours, supporting our finding that increased ITGAV was exported into the cancer‐derived EVs in metastatic tumours in vivo." (PMID 35923105, 2022). "Tumor genes COL5A2 and ITGAV expression also correlated with overall survival in the epithelioid subtype, demonstrating that epithelioid MESO can acquire EMT characteristics affecting survival before being categorized as biphasic." (PMID 35046456, 2022). "Results showed that ITGAV (10/10), ITGA2 (7/10), ITGA3 (8/9), ITGA4 (7/10), ITGA6 (7/8), and ITGA11 (7/9) protein levels were increased in tumour tissues compared with adjacent tissues." (PMID 34709754, 2021). "In summary, our study establishes that ITGAV is highly expressed in ESCC and promotes tumour progression." (PMID 34709754, 2021). "In the univariable Cox analysis, clinical tumor stage, age, and the expression levels of NFE2L2, ITGAV, GET4, FERMT2, CRB3, CDH2, and BCL2L1 were prognostic factors for OS." (PMID 33850477, 2021). "As expected, integrins interacting with ECM components are expressed in a cell‐type‐selective fashion, such as ITGA4, ITGAL and ITGB7 by immune cells, while tumour and stromal cells strongly expressed ITGA3, ITGAV and ITGB1/4/5/6/8." (PMID 34841720, 2021). "Based on these results, ITGA2, ITGAV, and GPC1 were used to isolate tumor-derived EVs in subsequent experiments." (PMID 34948417, 2021). "Log scale analyses showed that ITGAV and ITGB8 transcripts were more strongly expressed in four out of 15 tumour samples compared to autologous proximal healthy lung tissues." (PMID 34471106, 2021). "In this study we show that ITGAV expression is detectable in 14% of the EAC cases, which is somewhat lower than revealed in other tumor entities by TMA technique." (PMID 33110104, 2020). "However, the effects in the group of primarily operated patients are clear and show a significantly shortened overall survival in cases with ITGAV expression, so that ITGAV may play a role as a prognostic tumor marker in the description of disease progression of EAC." (PMID 33110104, 2020).
tumor (continued). "The products of two differentially regulated integrins, ITGAV and ITGB3, form the αVβ3 heterodimer, an integrin pair previously shown to regulate tumor cell survival and tumor metastasis in a ligand-independent fashion." (PMID 26918447, 2016). "Consistently, ITGAV silencing or GRGDS treatment significantly inhibited the seeding and outgrowth of tumor cells in fibrotic lungs in vivo." (PMID 27329720, 2016). "In line with the in vitro observations, knockdown of ITGAV or treatment with GLPG0187 significantly inhibited metastasis and secondary tumor growth in vivo." (PMID 25247809, 2014). "In line with these in vitro observations, knockdown of ITGAV or treatment with GLPG0187 significantly inhibited metastasis and secondary tumor growth (in bone marrow)." (PMID 25247809, 2014). "In short, we identified an exclusive tumor cell subpopulation MP3 in D‐TGCT and confirmed the role of these tumor cells in regulating differentiation of CD34+ Fbs toward APOE+ Fbs and MMP3+ Fbs through COL6A3 − (ITGAV + ITGB8) interaction." (PMID 40126353, 2025). "Similarly, ITGAV, PDGFC, PDGFD, and COL1A1—the most abundant collagen in human tissues—are often highly expressed in tumor cells, and inhibiting their expression can effectively suppress cell proliferation, migration, and invasion." (PMID 41227351, 2025). "Compared to naïve HL-60 human promyelocytic leukemia cells, which cannot be engulfed by tumor cells, differentiated HL-60 (dHL-60) neutrophils, which can be engulfed by tumor cells, express several integrin family genes, such as ICAM-1, ITGAM, ITGB2, ITGAX, and ITGAV, at higher levels." (PMID 39941753, 2025). "In our integrated analysis, we discovered a unique subpopulation of tumor cells (MP3 cluster) in D‐TGCT that could regulate differentiation of CD34+ Fbs into MMP3+ Fbs and APOE+ Fbs through the COL6A3 − (ITGAV + ITGB8) ligand–receptor pair." (PMID 40126353, 2025). "Research has shown that ITGAV can interact with CSPG4, regulating the microenvironment of Glioma Initiating Cells (GICs) by upregulating Integrin-ERK/MAPK signaling, thereby promoting the maintenance and differentiation of GICs and leading to tumor formation." (PMID 39239559, 2024). "Additionally, RT‐qPCR analysis indicated that CHST9 was expressed at low levels in tumour samples, while HMGN4, ITGAV, RAP2A, TMCO3, and ZFYVE26 displayed high expression levels." (PMID 39428564, 2024). "We observed that tumor growth was not delayed after ITGAV abrogation, despite cancer cells retained ITGAV down-regulation during tumor growth." (PMID 39075581, 2024). "The analysis suggested that TECs might promote tumor growth and progression through the interaction of COL4A1/COL4A2 with their partner receptors (ITGAV + ITGB8 and ITGA3 + ITGB1) on epithelial cells." (PMID 39093451, 2024). "The expression of ITGAV, ITGB3, and ITGB5 in EwS was comparable to other tumor entities." (PMID 38318175, 2024). "Tumor cell genes COL5A2 and ITGAV expression correlated with overall survival in MESO cohort." (PMID 35046456, 2022). "In published studies, AGRN, ITGAV, FLNC, ILK, and RSU1 were overexpressed in HCC tumor tissues, thereby promoting tumor development, metastasis, and even leading to poor prognosis, which is consistent with our findings." (PMID 36110210, 2022). "Given that ITGAV can be expressed on tumor surfaces, ITGAV is may be a potential target for CAR–T therapy, but future research is needed, Therefore, ITGAV is of great value as a future possible immunotherapy target." (PMID 36388191, 2022). "Among the 30 tumor samples, 7 (23.3%) were negative and 23 (76.7%) were positive in immunohistochemistry.We performed IHC to test ITGAV protein expression in LGG tissues and their counterparts and to examine the expression of ITGAV in LGG." (PMID 36388191, 2022). "A total of 36 samples were used for immunohistochemistry, including 6 normal tissues and 30 tumor tissues, of which 6 were negative for ITGAV protein expression." (PMID 36388191, 2022).
tumor (continued). "Since the EMT is considered the crucial step in tumor metastasis, blocking the EMT might lead to impairment of the migrative and clonogenic capacity following knocking down ITGAV." (PMID 33408774, 2021). "In addition, gene expression in the primary tumor (T-TIS) was higher compared to control (N-TIS) for most genes (TGFβ1, COL1A1, COL3A1, ITGAV, ITGAX) (matched samples)." (PMID 33718208, 2021). "The numbers of circulating tumor cells in the animals’ peripheral blood decreased due to the ITGAV KD, albeit not reaching statistical significance." (PMID 34174926, 2021). "Even more importantly, the effects of the absence of host selectins and ITGAV were synergistic, as clearly demonstrated in our intraperitoneal tumor model." (PMID 34174926, 2021). "Among them, 13 proteins correlated with clinicopathological parameters and of these proteins, eight proteins were identified in neoplastic islands (ACTR2, CSTB, COL1A2, LTA4H, PGK1, NDRG1, S100A8, S100A9) and five proteins were identified in tumor stroma (COL6A1, FSCN1, ITGAV, MB, THBS2)." (PMID 30185791, 2018). "Cystatin-B (CSTB), leukotriene A-4 hydrolase (LTA4H), protein NDRG1 (NDRG1), and phosphoglycerate kinase 1 (PGK1) from the neoplastic island dataset and collagen alpha-1(VI) chain (COL6A1), integrin alpha-V (ITGAV) and myoglobin (MB) from the tumor stromal dataset were prioritized." (PMID 30185791, 2018). "However, with this significant increase in the size cohort, LTA4H, PGK1, and ITGAV staining were identified with a slight variation within the lower and higher scores in each region, either ITF or inner tumor." (PMID 30185791, 2018). "Many of these genes, including those encoding bFGF, MAPK10, MAP3K5, IL1R2, E-cadherin, Ki67, Cyclin E1, beta-catenin, 14-3-3 protein T-cell (YWHAQ), integrin alpha-V (ITGAV), integrin alpha-10 (ITGA10), CDK6, PCNA, CDKN1A, and PAK3, are related to tumor metastasis and regulation of cell migration." (PMID 28454092, 2017). "Moreover, ligands implicated in the interaction between THBD+ macrophages and malignant tumour cells were identified, including SPP1‐(ITGAV+ITGB1) and APP‐CD74, suggesting the potential of THBD+ macrophages to influence malignant tumour cells through diverse ligands." (PMID 38809929, 2024). "In addition, to further verify the protein level of NPC2 and ITGAV expression, we compared the IHC results from the HPA database; and we found that the NPC2 and ITGAV proteins were expressed higher in tumor tissues than the normal ones." (PMID 39690926, 2024). "Additionally, we found that indomethacin exerts anti‐tumour activities using the PDX mouse model, especially in tumours with increased ITGAV protein levels, without causing significant body weight loss in mice." (PMID 34709754, 2021). "The administration of ODZ10117 dramatically decreased the tumor population and the levels of active STAT3, CSC markers such as NESTIN and SOX2, and MES-associated genes FN and ITGAV without significantly affecting the body weight compared to the vehicle-treated control group." (PMID 32183406, 2020). "The negative correlation between ITGAV expression and tumor purity further suggests that elevated ITGAV levels may foster a more immune-enriched microenvironment, potentially improving patient prognosis and increasing the efficacy of immunotherapy, especially in COAD and PRAD." (PMID 40775249, 2025). "Conversely, ITGAV showed a negative correlation with Th17 cells suggesting that it may be related to pathways inhibiting the infiltration of Th17 cells, thereby fostering an environment conducive to tumor growth." (PMID 40018050, 2025). "Indeed, the tumor cores (L and LB) were found to express numerous pEMT genes at significantly greater levels than the TME, including the laminins (LAMC1, LAMC2, LAMA3), integrins (ITGA2, ITGB1, ITGAV), and inflammatory and neutrophil-attracting chemokines (CXCL8, CXCL1)." (PMID 36216799, 2022).
tumor (continued). "High expressions of tumor cell genes COL5A2 and ITGAV and non-tumor cell genes SPARC and ACTA2 are both positively correlated with poor overall survival and disease-free survival in MESO cohort." (PMID 35046456, 2022).